MMP2 (matrix metallopeptidase 2)
Diseases named in the same sentence as MMP2 in open-access papers (continued):
Sharing a sentence is not in itself a finding about the gene and the disease.
lung carcinoma (continued). "Another study showed that by inducing TIMP-2 expression and decreasing TGF-1, Wogonin inhibited the activity of MMP-2, APN and EGFR-TPK, activated caspase 3, and played an important role in the metastasis and apoptosis of lung cancer A549 cells." (PMID 34630106, 2021). "Gene 33 expression has an inverse relationship with tyrosine phosphorylation of EGFR and the expression of metalloproteases MMP-2 and MMP-9 in lung cancer cells, suggesting a role of Gene 33 in lung cancer cell migration, invasion, and metastasis." (PMID 34206547, 2021). "PVT1 also increased the expression of MMP‐2 and MMP‐9 to promote EMT, which ultimately made lung cancer cells radioresistant." (PMID 33931980, 2021). "Highly expressed MMP-2 and MMP-9 have been found in lung cancer tissue and are closely related to poor prognosis in patients with lung cancer." (PMID 33758209, 2021). "In contrast, treatment with ginsenoside Rh2 decreased the secretion and expression of VEGF-C, MMP-2 and MMP-9 and inhibited the proliferation and migration of lung cancer cells." (PMID 34639167, 2021). "Our results demonstrate that Sal suppresses TGF-β1-induced EMT by downregulating MMP-2 and MMP-9 through the AMPK/SIRT pathway, thereby inhibiting lung cancer cell migration and invasion." (PMID 33437206, 2021). "This also upregulates HOXA10, MMP‐2, and MMP‐9, contributing to migration of lung cancer cells and ultimately reducing radiosensitivity." (PMID 33931980, 2021). "MMP2, MMP9 and MMP13 have been found upregulated and enhance the migration capability of lung cancer cells." (PMID 34820358, 2021). "MMP-28 overexpression in vitro lead to increased MMP-2 and MMP-14 mRNA levels, constitutive MMP-2 activation, and revealed e-cadherin as a high-affinity substrate for proteasomal degradation in lung carcinoma cells." (PMID 34255809, 2021). "The present study indicated that EZH2 knockdown decreasedthe expression of MMP2/9, suggesting that EZH2 knockdown exerted tumor suppressor role in lung cancer cells." (PMID 31855281, 2020). "Past studies have found that MMP2 and MMP9 were highly expressed in lung cancer and essential for the growth and metastasis of lung tumors." (PMID 33304892, 2020). "Previous reports also indicated that the downregulation of MMP-2 and MMP-9 inhibits the invasion and metastasis of lung cancer cells." (PMID 32349289, 2020). "It has been previously reported that TLR4-induced autophagy activation promoted migration and invasion of lung cancer by induction of chemokines and immunosuppressive factors including CCL2, CCL20, IL-6, VEGFA, and MMP2." (PMID 32384667, 2020). "Based on the previous reports regarding the role of air pollutants on the MMP activity in pulmonary diseases, we investigated the MMP-2 and MMP-9 expressions in PM10-exposed A549 lung cancer cells." (PMID 33374928, 2020). "Previous studies have demonstrated that the suppression of STAT3 phosphorylation and VEGF expression, as well as inhibition of MMP-2 and MMP-9, contributes to alleviating the invasion and angiogenesis process of lung cancer cells by curcumin." (PMID 33511113, 2020). "Good correlations have been observed between levels TSP‐2 and MMP‐2 expression in prostate cancer, and TSP‐2‐induced modulation of MMP‐13 expression in lung cancer cells regulates tumour metastasis." (PMID 33021341, 2020). "BCA could effectively inhibit the proliferation of lung cancer cells by downregulating Ki-67, induce apoptosis by activating the cleavage of caspase-3 and caspase-9, and suppress cell migration by downregulating matrix metallopeptidase-2 (MMP-2) and vascular endothelial growth factor (VEGF)." (PMID 31354500, 2019). "We selected the representative markers of tissue invasion and metastasis, MMP-2 and MMP-9 up-regulate lung cancer migration under microgravity conditions." (PMID 31601869, 2019). "Positive correlations between AQP3, MMP2, and MMP9 and cancer invasiveness also occur in lung cancer." (PMID 29922644, 2018).
lung carcinoma (continued). "SLIT3 was also induced by a DNA methylation inhibitor, and silencing of SLIT3 promoted proliferation, migration, and invasion with enhanced expression of MMP2 and MMP9 in lung cancer cells." (PMID 30613364, 2018). "We therefore performed the present study to evaluate the expression of MMP-2 and TIMP-2 in airways of lung cancer patients by comparing levels of them in benign diseases." (PMID 29113325, 2017). "MiR-98 overexpression suppressed lung cancer cell migration and invasion by inhibiting LIN28A-induced MMP2 and MMP9 expression." (PMID 28587210, 2017). "The results of this study demonstrate for the first time that curcumin-induced miR-98 expression inhibits MMP2/9 expression via modulation of LIN28A and consequently, human lung cancer cell growth in vitro and in vivo." (PMID 28587210, 2017). "The upregulation of MMP-2 and MMP-9 is one of the mechanisms through which Skp2 promotes lung cancer cell invasion." (PMID 29207614, 2017). "In this study, curcumin was confirmed to block lung cancer progression via modulation of miR-98, LIN28A, and MMP2/9 levels." (PMID 28587210, 2017). "In conclusion, our study showed that the levels of MMP-2 and TIMP-2 were significantly higher in lung cancer patients than that of benign diseases." (PMID 29113325, 2017). "Daurinol treatment resulted in suppression of MMP2 and MMP9 as well as down-regulation of FAK phosphorylation in both breast and lung cancer cells." (PMID 28915654, 2017). "Overexpression of NMI induced apoptosis, suppressed lung cancer cell growth and migration, which were mediated by up-regulation of the cleaved caspase-3/9 and down-regulation of phosphorylated PI3K/AKT, MMP2/MMP9, β-cadherin, and COX-2/PGE2." (PMID 29025423, 2017). "Recently, numerous studies have demonstrated that MMP-2 and TIMP-2 were involved in lung cancer development and prognosis." (PMID 29113325, 2017). "MMP family of proteinases, particularly MMP-1, MMP-2 and MMP-9 expressed in lung cancer, play an important role in malignant tumor metastasis." (PMID 28915603, 2017). "Nickel chloride promotes the invasive potential of human lung cancer cells through elevated IL-8, TGF-β, MMP2 and MMP9 expression." (PMID 29127306, 2017). "The results showed a higher level of MMP-2 and TIMP-2 expression and secretion in airways of lung cancer patients than that of benign diseases." (PMID 29113325, 2017). "Recent findings have confirmed that in lung cancer cells, siRNA-TMEM98 significantly suppressed the invasion and migration of human A549 and H460 cells through down regulating MAT1, MMP-2, MMP-9 and RhoC." (PMID 29152140, 2017). "In contrast, knockdown of NMI promoted lung cancer cell colony formation and migration, which were correlated with the increased expression of phosphorylated PI3K/AKT, MMP2/MMP9, β-cadherin and COX-2/PGE2." (PMID 29025423, 2017). "Levels of VEGF, IL-8, matrix metallo-protease-9 (MMP-9) and MMP-2 were measured in serum samples of COPD and lung cancer patients, which were compared with HD." (PMID 27811960, 2016). "In these patients, except for MMP-2, the levels of other biomarkers (VEGF, IL-8 and MMP-9) followed a close proximity to COPD and lung cancer patients, but clearly differed from HD." (PMID 27811960, 2016). "Resveratrol suppressed NF-κB activity leading to inhibition of HO-1 and subsequently downregulating the expression of MMP-2 and MMP-9 in lung cancer cells." (PMID 27834913, 2016). "On the basis of our results, fucoidan is able to mediate the activities of MMP-2 and MMP-9, also in line with the report that fucoidan suppressed migration and invasion of A549 lung cancer cells by suppressing secretion and/or expression of MMP-2." (PMID 25854641, 2015). "While expression of MMP-2 and MMP-9 have been characterized extensively in lung cancer, much less is known about MMP-13." (PMID 26193700, 2015). "EFEMP1 negatively modulates the invasiveness of lung cancer cells by regulating p38-MAPK and MMP-2/9/7." (PMID 25987128, 2015).
lung carcinoma (continued). "Fucoidan was also reported to be an antitumor compound inhibiting migration, invasion and MMP-2/-9 activities in human fibrosarcoma cells (HT1080), human lung cancer cells (A549) and mouse hepatocarcinoma cells lines (Hca-F)." (PMID 26133555, 2015). "In lung cancer, uPA, its receptor (uPAR), and the inhibitors PAI-1 and PAI-2 of the plasminogen activator family interact with MMP-2 and MMP-9 of the MMP family to promote cancer progression." (PMID 26230665, 2015). "A carefully done study of 63 patients who had surgery for lung cancer or lung transplantation demonstrated that increasing TIMP-1 and MMP-2 mRNA in the small airways and/or the parenchyma surrounding the small airway was positively associated with FEV1." (PMID 24447332, 2014). "Suppression of MMP-2 decreases integrin-αvβ3-mediated induction of PI3K/AKT, thus leading to decreased VEGF-A expression in lung cancer cells." (PMID 25233229, 2014). "Constitutive phosphorylation of Akt at serine 473 (AktS473) by transfecting lung cancer cells with dominant active Akt plasmid (pAkt-DA) increased the EMT, MMP2 activity and invasion ability of cancer cells and increased expression of COX-2 and MIG-7." (PMID 25004182, 2014). "The down regulation of MMP-2 and -9 occurs through MEKK and ERK signaling pathways in A549 lung cancer cells." (PMID 25566531, 2014). "Recently, ectopic overexpression of MMP2 in MCF7 cells was shown to result in enhanced motility and invasiveness in breast, ovarian and lung cancer cells." (PMID 25208219, 2014). "Initially, we focused on MMP2 and MMP9, because high expression of MMP2 or 9 is commonly observed in various cancers including lung cancer, and their expression is positively correlated with tumor malignancy and poor diagnosis of cancer patients." (PMID 24318272, 2013). "We provide important evidence that that miR-29c can suppress lung cancer cell adhesion to ECM and metastasis by targetting the 3′-UTR of integrin β1 and MMP2 mRNA to down-regulate their protein expression." (PMID 23936390, 2013). "HPV 16 E6 up-regulates pro-angiogenic MMP-2 and MMP-9 through inducing IL-8 expression in lung cancer cells." (PMID 23349885, 2013). "Taken together, our results demonstrate that miR-29c serves as a tumor metastasis suppressor, which suppresses lung cancer cell adhesion to ECM and metastasis by directly inhibiting integrin β1 and MMP2 expression and by further reducing MMP2 enzyme activity." (PMID 23936390, 2013). "In conclusion, our results indicate that overexpression of VEGF enhances the growth of Lewis lung cancer cells, stimulates the production of COX-2, MMP2, MMP9 and enhances the functional activities of MMP2 and MMP9 in vitro." (PMID 23226772, 2012). "The gene expression level of VEGFA, PGF, and their receptors FLT1 and KDR as well as MMP-2 and the inhibitors TIMP-1 and TIMP-2 was higher in samples from lung cancer resections compared to pneumothorax and transplant biopsy samples." (PMID 22593690, 2012). "Despite the high gene expression levels of VEGFA, PGF, FLT1, KDR, MMP-2, TIMP-1, and TIMP-2, only KDR and TIMP-1 were high at the protein level in the lung cancer resections." (PMID 22593690, 2012). "There was weaker staining of MMP-2 and VEGFA in the transplant biopsies, and the levels of PGF were found to be lower in lung cancer resections." (PMID 22593690, 2012). "However, we could not observe any relation between snail and these MMPs in the array material with all results indicating that there was no evident association between MMP2 and 9 and snail in lung carcinoma." (PMID 23157169, 2012). "In conclusion, it is the first time that fucoidan is revealed to inhibit MMP-2 activity via the suppression of PI3K-Akt-mTOR and NF-kB signaling pathway in A549 lung cancer cells, resulting in the down regulation of cancer cell migration and invasion." (PMID 23226337, 2012). "Similarly, Skp2 also increases the expression of MMP-2 and MMP-9 to promote invasion of lung cancer cells." (PMID 41385185, 2025).
lung carcinoma (continued). "The results imply that p38-MAPK activation is critical in regulating MMP-2 expression while simultaneously acting as a negative regulator of hsa-miR-125b-5p in lung cancer cells." (PMID 41155277, 2025). "Similarly suppression of BMP-1 expression reduces the activity of TGF-β, downregulates MMP2/MMP9 expression and decreases the invasion of lung cancer cells." (PMID 39792296, 2025). "Similarly, exosmal miR‐494 and miR‐542‐3p from pulmonary interstitial cells down‐regulate the expression of cadherin‐17, thus increasing the expression level of matrix metalloproteinase MMP2 and MMP3 and promoting the distant metastasis of lung cancer cells." (PMID 39548655, 2024). "In addition, C35 possessed a significant inhibition of migration by reducing the expression of matrix metalloproteinases-2 (MMP-2) and MMP-9 in lung cancer cells." (PMID 38776295, 2024). "Therefore, the protein expression of MMP-2 and MMP-9 in lung cancer cells in response to C35 treatment were evaluated through Western blot and ELISA." (PMID 38776295, 2024). "EGCG loaded with poly(lactic-co-glycolic acid) (PLGA) nanoparticles suppressed the NF-κB pathway and inhibited the mRNA expression of several downstream molecules, such as MMP-2, cyclooxygenase-2 (COX-2), and tumor necrosis factor α (TNF-α), in the lung cancer cell lines A549 and H1299." (PMID 39335164, 2024). "Clinical trials targeting MMP-2 modulation highlight the potential of gelatinase inhibitors, including those targeting MMP-2, to reduce tumor progression in fibrosarcoma, breast, and lung cancers." (PMID 39769454, 2024). "However, the number of published genotypic articles on the role of MMP-2 and MMP-9 in lung cancer has been extremely low in the preceding decade." (PMID 37445754, 2023). "We found that propionate inhibited TLR2- and TLR3-induced lung cancer migration, invasion, and colony formation accompanied by the inhibition of the cAMP-AMPK-TAK1 signaling axis for the activation of NF-κB and the production of CCL2, IL-6, and MMP2 cytokines." (PMID 37287005, 2023). "Previous studies of our group showed that MMP2 and MMP9 were major MMPs secreted by murine tumor cells derived from Lewis lung cancer cells by gelatin zymography and affinity chromatography demonstrated that these MMPs were bound by EGCG immobilized on agarose gel." (PMID 36677584, 2023). "For the first time, we designed a cationic peptide with a mirrored RGD modification, featuring four arginine residues at both ends of the MMP2‐cleavable peptide PLGLAG (RGDGSRRRRPLGLAGRRRRGSRGD, RD24), which was used to carry the lung cancer suppressive miRNA, miR‐148a‐3p." (PMID 37521428, 2023). "For instance, a rise in serum MMP-2 levels has been identified in advanced stages of nonsmall cell lung cancer (NSCLC) compared with nonmetastatic lung cancer and control subjects." (PMID 36213817, 2022). "Previous reporters have shown that THBS2 could regulate MMP-2 and MMP-13 to promote tumor metastasis of prostate cancer and lung cancer." (PMID 36118676, 2022). "The excessive expression of MMP-2 and MMP-9 is also highly correlated with lung cancer metastasis." (PMID 35711540, 2022). "We found that although the expression of MMP2 in lung cancer tissues did not increase, the expression level of MMP9 tended to increase (P=0.08)." (PMID 35371324, 2022). "Elastin peptide VGVAPG has been shown to stimulate fibrosarcoma cell invasion through the activation of MMP-2 and uPA, upregulate MMP-14 and stimulate the angiogenic phenotype of endothelial cells and increase the invasiveness of lung cancer cells by post-transcriptional regulation of MMP-2 and uPA." (PMID 35008401, 2022). "Additionally, the mRNA expression and protein levels of Snail, MMP2, and MMP9 are decreasing in lung cancer cells treated by rhein." (PMID 35178453, 2022).
lung carcinoma (continued). "Besides, miR-182-5p upregulated the expression of Twist, MMP-2 (matrix metallopeptidase 2), MMP-9 (matrix metallopeptidase 9), N-cadherin, Vimentin, and Snail proteins, which promoted the EMT process in lung cancer." (PMID 34729113, 2021). "Specifically, in lung cancer, FOXM1 has been found to be co-expressed with CENE and could regulate the expression of MMP2, contributing to LUAD growth and metastasis." (PMID 35036134, 2021). "In the present study, we showed that MMP-2 and MMP-9 activity mediates Sal's anti-invasive and anti-migratory effects by downregulation through the AMPK/SIRT pathway, thereby inhibiting the invasion and metastasis of lung cancer cells." (PMID 33437206, 2021). "The mesenchymal markers Matrix metalloproteinase-2 (MMP2), Vimentin, N-cadherin, Snail and Slug were significantly down-regulated, whereas the epithelial markers E-cadherin was notably upregulated by FOXH1 depletion in both lung cancer cell lines." (PMID 34090445, 2021). "Moreover, miR-106b enhanced the expression of MMP-2 and MMP-9 and targeted PTEN to promote lung cancer cell migration and invasion." (PMID 34281588, 2021). "Our results showed that epigenetic regulation of CD44v6, Nm23-H1, MMP-2, and MMP-9 might be involved in the pathogenesis and metastasis of lung cancer." (PMID 34400947, 2021). "There are reports that BAP31 knockdown reduces expression level of TGF-β1, MMP-2, MMP-9, ROCK1, α-SMA, Vimentin and N-cadherin in cervical cancer, and BAP31 affects F-actin distribution to promote migration and invasion of lung cancer cells." (PMID 34179078, 2021). "Depletion of ABL1 and ABL2 protein kinases in PC9-AA and HCC827-AA lung cancer cells impaired the increase of MMP9 but not MMP2 gelatinase activity induced by MSCs." (PMID 33119681, 2020). "The expression of MMP2 was higher in lung cancer tissues than that in adjacent non-malignant tissues (p = 0.002)." (PMID 33115469, 2020). "In contrast, MMP2 gelatinase activity was not altered in lung cancer cells primed by MSCs under co-culture conditions." (PMID 33119681, 2020). "Thirdly, this study did not concern the specific mechanisms by which MMP2 affects the growth, proliferation and metastasis of lung cancer cells." (PMID 33115469, 2020). "Further, knockdown of RPS6 in SK-MES-1 and H1650 lung cancer cells reduced their invasive ability and decreased MMP9 and MMP2 expression, suggesting that high levels of RPS6 may promote lung cancer metastasis." (PMID 32862831, 2020). "Thus, suppression of migration and invasion is triggered by promoting HDAC6-mediated HSP90/MMP-2 or MMP-9 dissociation and followed by MMP-2 and MMP-9 degradation in breast and lung cancer cells." (PMID 32961679, 2020). "Expression of MMP2 was not related to the sex, age, smoking status and histology of lung cancer (p > 0.05)." (PMID 33115469, 2020). "The expression of MMP2 in lung cancer tissues and in adjacent non-malignant tissues was tested by immunohistochemistry." (PMID 33115469, 2020). "Similar results were observed upon co-culture of HCC827 lung cancer cells with MSCs resulting in enhanced MMP9 but not MMP2 gelatinase activity." (PMID 33119681, 2020). "Previous studies have shown that IOP can change energy metabolism through the LKB1/AMPK pathway and induce lung cancer cell apoptosis; IOP can also reduce the expression of MMP-2 and MMP-9 by downregulating the NF-κB signaling pathway, thereby inhibiting the migration and invasion of B16-F10 cells." (PMID 33282634, 2020).